P3R3URF (PIK3R3 upstream open reading frame)
Gene: Protein-coding gene on chromosome 1 (46,175,486 to 46,176,488, reverse strand). Ensembl gene ENSG00000250719.
Gene Ontology:
Biological process: cytokine-mediated signaling pathway
Genetic constraint (gnomAD): Loss-of-function variants: 6 observed, 8.41 expected, observed/expected ratio (o/e) 0.71, 90% interval 0.39 to 1.4. That is too few expected variants to judge how well the gene tolerates losing a copy. Missense variants: 121 observed, 122.03 expected, observed/expected ratio (o/e) 0.99, 90% interval 0.86 to 1.15. Synonymous variants: 39 observed, 38.3 expected, observed/expected ratio (o/e) 1.02, 90% interval 0.79 to 1.33.
Homologues: Orthologues: chimpanzee P3R3URF (99% identical), dog P3R3URF (72% identical), rabbit P3R3URF (68% identical), pig P3R3URF (67% identical), rat P3r3urf (63% identical), mouse P3r3urf (61% identical), guinea pig P3R3URF (58% identical).